FNDC5 (fibronectin type III domain containing 5)
Diseases named in the same sentence as FNDC5 in open-access papers (continued):
Sharing a sentence is not in itself a finding about the gene and the disease.
gastrointestinal tract cancers (1 paper, 2019). "One study showed increased FNDC5 immunoreactivity in several gastrointestinal tract cancers including CRC." (PMID 31093274, 2019).
FNDC5 also shares sentences with these, for which no sentence is quoted: cognitive disorder (3 papers); adenocarcinoma (2); amyotrophic lateral sclerosis (2); cervical cancer (2); diabetic cardiomyopathy (2); Glucose intolerance (2); hypertriglyceridemia (2); Impaired glucose tolerance (2); kidney disease (2); Anorexia (1); Anxiety (1); bladder cancer (1); blood pressure (1); bone cancer (1); breast neoplasm (1); Cachexia (1); calcification (1); cervical adenocarcinoma (1); chronic obstructive pulmonary disease (1); colon adenocarcinoma (1); diabetic neuropathies (1); end-stage renal disease (1); Ewing sarcoma (1); fibromyalgia (1); glioma (1); glomerulosclerosis (1); Huntington disease (1); hyperphosphatemia (1); Idiopathic Inflammatory Myopathies (1); intestinal type adenocarcinoma (1).
A further 15 diseases each share a sentence with FNDC5 in 1 paper.